MAGED2 (MAGE family member D2)
Diseases named in the same sentence as MAGED2 in open-access papers (continued):
Sharing a sentence is not in itself a finding about the gene and the disease.
Polyhydramnios (2 papers, 2021 to 2026). The presence of excess amniotic fluid in the uterus during pregnancy. "The typical features of aBS are reflected by the early onset of polyhydramnios and postnatal polyuria, which has been shown to be caused by mutations in the MAGED2 gene (melanoma-associated antigen D2); the protein is not a solute carrier but a regulatory protein with function not fully understood." (PMID 34926352, 2021). "In fetuses presenting with early-onset severe polyhydramnios (around 19-20 weeks of gestation), particular attention should be paid to possible exon-level or partial deletions involving MAGED2 during genetic evaluation." (PMID 42074542, 2026).
triple-negative breast carcinoma (2 papers, 2019 to 2024). An invasive breast carcinoma which is negative for expression of estrogen receptor (ER), progesterone receptor (PR), and human epidermal growth factor receptor 2 (HER2). "MAGED2 participates in cell cycle regulation and participates in the process of methionine deprivation which leads to a targetable vulnerability in triple-negative breast cancer cells by promoting Trail receptor-2 expression." (PMID 31534839, 2019).
anaplastic astrocytoma (1 paper, 2022). "MAGED2 mRNA was highest in glioblastoma (p < 0.001), and diffuse astrocytoma had the second-highest value (p < 0.001)—followed by oligodendroglioma (p < 0.001) and anaplastic astrocytoma (p < 0.001)—when compared with normal brain tissue." (PMID 35892426, 2022).
Bartter syndrome type V (1 paper, 2025). "To gain further insight into the role of MAGED2 in renal salt reabsorption associated with Bartter syndrome type V (tBS), we initially investigated the effect of MAGED2 on the localization of the NCC under normoxic and hypoxic conditions in HEK293 cells." (PMID 39936967, 2025). "Bartter syndrome type V, the most severe form of BS, is caused by X-linked mutations in MAGED2." (PMID 39936967, 2025).
COVID-19 (1 paper, 2022). A disease caused by infection with severe acute respiratory syndrome coronavirus 2. "We speculate that the high expression of these immune-related genes can alleviate the aggravation of COVID-19 symptom severity, such as GAGE12F, TNMD, MAGEA6, MAGED2, and XAGE1A." (PMID 36118230, 2022).
Intellectual disability (1 paper, 2023). "Interestingly, MAGED2 is a hotspot for X chromosome-linked intellectual disability." (PMID 37834424, 2023).
lymphoma (1 paper, 2021). A malignant (clonal) proliferation of B- lymphocytes or T- lymphocytes which involves the lymph nodes, bone marrow and/or extranodal sites. "Although it is unclear whether MAGED2 mutations affect tumour progression in lymphoma, studies from different fields confirmed that some of these gene mutations play a role in cell cycle progression and apoptosis." (PMID 33752626, 2021).
meningioma (1 paper, 2020). A generally slow growing tumor attached to the dura mater. "This study revealed the identification of phosphorylated sites of several proteins that were found to play a role in meningioma pathobiology by several studies including EPB41L2, NDRG2, SPTB, MAGED2, MXRA7, and nearly 51 Kinases which were also mapped further through Kinome Analysis." (PMID 32974197, 2020).
viral infection (1 paper, 2023). "However, MAGED2 function in virus infection is poorly understood." (PMID 37439567, 2023). "However, the biological role of MAGED2 in virus infection has been less characterized." (PMID 37439567, 2023). "In addition, the interaction of endogenous MAGED2 with viral N protein could also be detected in the viral infection context, and it seems that the interaction is dependent on RNA as the interaction could be disrupted by RNase A treatment." (PMID 37439567, 2023). "Our results showed that overexpression of MAGED2 inhibited SARS-CoV-2 infection, as evidenced by a decreased percentage of viral infection cells." (PMID 37439567, 2023).
cancer (17 papers, 2013 to 2024). A tumor composed of atypical neoplastic, often pleomorphic cells that invade other tissues. "For cancer related genes, Nav3, Cenpf, Muc5Ac, Mpp7, Gas1, MageD2, Dusp1, Ros, Polr2a, Rragd, Ros1, and Hoxa9 are mutated." (PMID 32793490, 2020). "Further mutations in cancer-related genes included Nav3 (V1129L), Cenpf (D1327E), Muc5ac (A429P), Mpp7 (Q158R), Gas1 (G326R), Maged2 (A473S), Dusp1 (C24R), Ros1 (W1875C), Polr2a (M1102I), Rragd (L385P), and Hoxa9 (insertion of “G” in UTR)." (PMID 32793490, 2020). "MAGED2 is a cell adherent molecule and belongs to the melanoma-associated antigen family, which plays important roles in cancer development, progression, and resistance to treatment." (PMID 29721160, 2018). "Melanoma antigen D2 (MAGED2) was recognized as a cancer diagnostic marker by changing intracellular localization and shuttling during cell cycle progression and in response to cellular stress." (PMID 28968955, 2017). "Of note, MAGED2 is also expressed in many human cancers and is associated with a poor prognosis." (PMID 36010623, 2022). "MAGED2 is also expressed in many human cancers and is associated with a poor prognosis." (PMID 36359819, 2022). "Analogously to the oncogenic potential of MAGEA3/A6 expression in tumors resulting in enhanced proliferation by limiting mTOR-dependent autophagy, a similar role of MAGED2 is conceivable, which is abundantly expressed in many types of cancers." (PMID 37686237, 2023). "Consistent with that, under both physical and chemical hypoxia, knockdown of MAGED2 in renal (HEK293) and cancer (HeLa) cell culture models caused internalization of Gαs, which was fully reversible upon reoxygenation." (PMID 36010623, 2022). "Many malignancies have high MAGED2 expression, and MAGED2 may play a vital role in cancer progression, making it a prospective target for tumor therapy." (PMID 35892426, 2022). "As a result, MAGED2 is expected to become a potential cancer target, and may play an important role in tumor progression." (PMID 35892426, 2022). "The key finding of this study is that MAGED2 is required under both physical hypoxia and treatment with the hypoxia mimetic CoCl2 to fully induce HIF-1α in renal (HEK293) and cancer (HeLa) cell culture models." (PMID 36359819, 2022). "We therefore examined the effects of MAGED2 knockdown on the intracellular localization of Gαs, and the cAMP/PKA pathway with and without physical and chemical hypoxia in a renal cell culture system (HEK293) and in a human cancer cell line (HeLa)." (PMID 36010623, 2022).
tumor (6 papers, 2015 to 2026). "Except for MAGED2, the expression levels of the remaining four genes were significantly higher in tumor tissues compared to normal tissues (P < 0.05)." (PMID 40129974, 2025). "In line with in vitro findings, the results of the xenograft experiment and immunohistochemistry also showed that MAGED2 suppression inhibited tumor development and decreased Ki-67 expression levels." (PMID 35892426, 2022). "The influence of MAGED2 expression and tumor categorization was analyzed using a Kaplan–Meier survival analysis to identify the prognostic value for MAGED2." (PMID 35892426, 2022). "When compared to the Scramble CRISPR group, the tumor volume in the MAGED2 CRISPR group was significantly reduced." (PMID 35892426, 2022). "Sex, age, tumor size (≥3.0 cm), extent of resection, WHO classification (High grade), IDH1 status (Mutant), Ki-67 expression (≥10%), and MAGED2 protein expression were used to categorize patients." (PMID 35892426, 2022).
infection (5 papers, 2022 to 2025). The state of being infected such as from the introduction of a foreign agent such as serum, vaccine, antigenic substance or organism. "MAGED2 mRNA (t = 4.47, p = 0.0012) and protein (t = 10.58, p < 0.000) levels in U251-MG cells of the MAGED2 CRISPR group were significantly lower than those in the Scramble CRISPR group 72 h after infection." (PMID 35892426, 2022). "However, MAGED2N(ΔNLS)-Flag, which localized in cytoplasm and was able to interact with viral N protein, exhibited comparable antiviral activity against SARS-CoV-2 trVLP infection with that of WT MAGED2." (PMID 37439567, 2023). "SARS-CoV-2 GFP/ΔN trVLP infected the Caco-2-N cells expressing MAGED2-Flag or mutants (MOI = 0.1), and then GFP was analyzed after 24 h of infection." (PMID 37439567, 2023). "Our results showed that MAGED2 knockout resulted in twofold increase of SARS-CoV-2 GFP/ΔN trVLP infection (percentage of GFP positive cells) compared with WT (non-targeting control) cells and increased copies of viral genomic RNA and subgenomic RNA." (PMID 37439567, 2023).
kidney disease (1 paper, 2022). "Given the well-established link between HIF-1α and cAMP/PKA and by showing in the present study that MAGED2 is also required for hypoxic induction of HIF-1α, the finding of the present study may further explain the transient nature of this kidney disease." (PMID 36359819, 2022). "In terms of therapeutic applications, inhibition of MAGED2 could target the oncoproteins Gαs and HIF-1α specifically in hypoxic tumors, and its activation may enhance HIF-1α induction in kidney disease." (PMID 36359819, 2022).
MAGED2 also shares sentences with these, for which no sentence is quoted: hypokalaemia (2 papers); lung carcinoma (2); anemia (1); chronic hepatitis (1); ciliopathies (1); Cirrhosis (1); colon carcinoma (1); colorectal cancer (1); colorectal tumors (1); cystic kidney disease (1); depression (1); diffuse astrocytoma (1); Gitelman syndrome (1); glioblastoma (1); Goblet cell carcinoids (1); hydrops (1); liver cancer (1); Obesity (1); oligodendroglioma (1); osteosarcoma (1); Polyuria (1); renal tubular disease (1); sideroblastic anemia (1); small intestinal carcinoid (1); teratocarcinoma (1).